WDR62 (WD repeat domain 62)
Diseases named in the same sentence as WDR62 in open-access papers (continued):
Sharing a sentence is not in itself a finding about the gene and the disease.
ovarian carcinoma (3 papers, 2013 to 2025). A malignant neoplasm originating from the surface ovarian epithelium. "In this study, we identified WDR62 as a potential biomarker for early screening and diagnosis of ovarian cancer and found it to be closely associated with poor patient prognosis." (PMID 40369663, 2025). "We propose that WDR62 overexpression is an important biomarker for the diagnosis and possibly associated with tumorigenesis of ovarian carcinoma." (PMID 23898938, 2013). "In this study, GO and GSEA enrichment analyses revealed that in ovarian cancer, the gene set associated with high WDR62 expression group was predominantly enriched in pathways such as MITOTIC_SPINDLE, G2M_CHECKPOINT, CELL_CYCLE, and DNA_REPLICATION, compared to the low-expression group." (PMID 40369663, 2025). "However, to date, only one study has investigated WDR62 in ovarian cancer, demonstrating that WDR62 overexpression is associated with centrosome amplification in human ovarian cancer." (PMID 40369663, 2025). "The analysis of the GEPIA2 database showed that WDR62 expression was significantly higher in ovarian cancer compared to normal ovarian tissue in TCGA and GTEx datasets." (PMID 40369663, 2025). "Our results demonstrate that reducing WDR62 expression in ovarian cancer cells significantly decreases the levels of cell cycle-related proteins CDK1 and C-Myc in vitro." (PMID 40369663, 2025). "The expression of WDR62 was effectively reduced by transfecting si-WDR62 into these ovarian cancer cell lines." (PMID 40369663, 2025). "Subsequently, we confirmed the high expression of WDR62 in ovarian cancer at RNA and protein levels by qPCR and Western blot experiments, respectively." (PMID 40369663, 2025). "The qRT-PCR results demonstrated that the mRNA expression level of WDR62 was significantly higher in ovarian cancer cell lines (A2780, SKOV3, HO8910, and OVCAR3) compared to normal ovarian epithelial cells (IOSE80)." (PMID 40369663, 2025). "WDR62 is overexpressed in ovarian cancer and is closely related to the prognosis of ovarian cancer patients." (PMID 40369663, 2025). "The ROC curve of TCGA and GTEx datasets verified the sensitivity and specificity of WDR62 as a biomarker for the diagnosis of ovarian cancer, with an area under the curve (AUC) equal to 0.977." (PMID 40369663, 2025). "In summary, WDR62 is overexpressed in ovarian cancer, correlates with poor patient prognosis, and promotes ovarian cancer development by regulating the cell cycle." (PMID 40369663, 2025). "Meanwhile, the results of the survival analysis showed that high WDR62 expression was associated with poorer OS, PFS, and PPS in ovarian cancer patients." (PMID 40369663, 2025). "Meanwhile, CCK8 results showed that the knockdown of WDR62 decreased the proliferative ability of ovarian cancer cells." (PMID 40369663, 2025). "GO and GSEA enrichment analysis, along with in vitro experiments, demonstrated that WDR62 promotes ovarian cancer development through cell cycle regulation." (PMID 40369663, 2025). "Other study implies WDR62 overexpression is an important molecular change, specifically related to ovarian cancer with centrosome amplification." (PMID 33937237, 2021). "WDR62 is overexpressed in most of the epithelial ovarian cancer cell lines and tumors, especially in high-grade carcinoma of the ovary." (PMID 33937237, 2021). "Our results show that WDR62 overexpression was significantly higher in high-grade carcinoma than in other types of ovarian cancer." (PMID 23898938, 2013).
ovarian carcinoma (continued). "Therefore, WDR62 overexpression may result in genetic instability that may not only predispose to the rapid development of epithelial ovarian cancer, but also predispose cells to further genetic alterations and heterogeneity with evolving resistance to therapy." (PMID 23898938, 2013). "Six ovarian cancer cell lines exhibited significant WDR62 protein overexpression, and amplification of centrosome." (PMID 23898938, 2013). "Our findings suggest that WDR62 overexpression is related to centrosome amplification in ovarian cancer." (PMID 23898938, 2013). "High-grade ovarian cancer specimens exhibited significantly stronger nuclear staining of WDR62 than low-grade ovarian carcinoma specimens (80.4% vs 41.3%; P<0.012)." (PMID 23898938, 2013). "In this study, WDR62 expression was assessed by western blot (6 ovarian cancer cell lines) and immunohistochemistry (primary epithelial ovarian cancer clinical specimens), and clinical variables were collected by retrospective chart review." (PMID 23898938, 2013). "In this study, we analyzed the DEGs base on combined TCGA and GTEx datasets from the UCSC database, then applied WGCNA to identify genes highly correlated with tumor progression, and then combined with survival prognostic analysis to identify WDR62 as a new potential biomarker for ovarian cancer." (PMID 40369663, 2025). "Combined with the previous discussion, MAPK8 is a key molecule in the JNK signaling pathway, and WDR62 may interact with MAPK8 to promote the progression of ovarian cancer." (PMID 40369663, 2025). "This suggests that WDR62 regulates the expression of cell cycle-related proteins in ovarian cancer." (PMID 40369663, 2025). "Additionally, the enrichment analysis of WDR62 was carried out by GSEA software based on the ovarian cancer data in the TCGA database, and according to the median expression of WDR62, it was divided into high-expression and low-expression groups." (PMID 40369663, 2025). "WDR62 promotes ovarian cancer progression by regulating the cell cycle and may influence its development through interaction with MAPK8 to mediate the JNK signaling pathway." (PMID 40369663, 2025). "Enrichment analysis, cell transfection, Western blots and CCK8 demonstrated the regulatory mechanism of WDR62, and the detailed mechanism of WDR62 involvement in the occurrence and development of ovarian cancer was predicted by interaction analysis and correlation analysis." (PMID 40369663, 2025). "This suggests that MAPK8 may play a critical role in ovarian cancer, further validating that WDR62 may interact with MAPK8 thereby promoting ovarian cancer progression." (PMID 40369663, 2025). "Given its role, WDR62 holds promise as a novel target for early screening, diagnosis, and treatment of ovarian cancer, which is undoubtedly of great significance in reducing the mortality rate of ovarian cancer." (PMID 40369663, 2025). "Interestingly, the WDR62 expression and average centrosome count of high grade ovarian cancer cells (OV-90) were significantly higher than others." (PMID 23898938, 2013). "These suggest that WDR62 may affect the progression of ovarian cancer by regulating the cell cycle." (PMID 40369663, 2025). "Notably, MAPK8 showed the highest correlation with WDR62 in ovarian cancer (R = 0.4, p < 0.05)." (PMID 40369663, 2025). "Therefore, this study found that WDR62 may be a promising target for early screening, diagnosis, and treatment of ovarian cancer and could be used to evaluate the prognosis of ovarian cancer patients." (PMID 40369663, 2025). "Additionally, interaction and correlation analyses suggest that WDR62 may affect ovarian cancer progression by interacting with MAPK8 (also known as JNK1) to mediate the JNK signaling pathway." (PMID 40369663, 2025). "Given the relationship between WDR62 and centrosome amplification found in various cancers, it is intuitive to hypothesize that WDR62 expression may critically mediate the development of human ovarian cancer." (PMID 23898938, 2013).
ovarian carcinoma (continued). "Therefore, we speculated that WDR62 might interact with MAPK8 in ovarian cancer." (PMID 40369663, 2025). "Upon WDR62 knockdown, the expression of cell cycle-related proteins CDK1 and C-Myc decreased in ovarian cancer cells, and the cell proliferative capacity was decreased." (PMID 40369663, 2025). "GEPIA2 database analysis showed that WDR62 is positively correlated with MKK4 and MKK7, key components of the JNK signaling pathway, in ovarian cancer." (PMID 40369663, 2025). "This confirmed that the knockdown of WDR62 reduced the proliferative ability of SKOV3 and OVCAR3 cell lines, further supporting its role in promoting ovarian cancer development through cell cycle regulation." (PMID 40369663, 2025). "This suggests that WDR62 might mediate the JNK signaling pathway through interacting with MAPK8 and thus regulate the cell cycle to affect the progression of ovarian cancer, but further experimental verification is needed." (PMID 40369663, 2025). "Based on bioinformatic analysis, it was hypothesized that WDR62 might mediate the JNK signaling pathway by interacting with MAPK8, thus affecting ovarian cancer progression through cell cycle regulation." (PMID 40369663, 2025). "In addition, the differential analysis of WDR62 expression in the GSE26712、GSE12470 and GSE18520 datasets further verified the high expression of WDR62 in ovarian cancer." (PMID 40369663, 2025). "WDR62 was highly expressed in ovarian cancer cells compared to normal ovarian epithelial cells, both at the RNA and protein levels." (PMID 40369663, 2025). "Further analysis suggests that WDR62 may interact with MAPK8 to mediate the JNK signaling pathway, and thus regulating the cell cycle to impact ovarian cancer progression." (PMID 40369663, 2025). "There is no in-depth research on the mechanisms through which WDR62 influences ovarian cancer occurrence and development." (PMID 40369663, 2025). "Therefore, we hypothesize that WDR62 interacts with MAPK8, thereby regulating the cell cycle and promoting the development of ovarian cancer." (PMID 40369663, 2025). "Pan-cancer analysis showed that WDR62 was highly expressed in a variety of tumors, and similarly, the expression level of WDR62 in ovarian cancer was significantly higher than that in normal ovaries in the TCGA-GTEx dataset, GSE26712, GSE12470, and GSE18520 datasets." (PMID 40369663, 2025).
breast carcinoma (2 papers, 2021 to 2022). "In breast cancer, with the highest morbidity now, we further analyzed the datasets and discovered a correlation between WDR62 expression and clinical features." (PMID 34306258, 2021).
lung carcinoma (2 papers, 2021 to 2025). "For example, WDR62 was significantly overexpressed in LAC, and lung cancer cell proliferation decreased after WDR62 knockdown and increased after overexpression." (PMID 40369663, 2025).
metastatic prostate carcinoma (2 papers, 2021 to 2023). A carcinoma that arises from the prostate gland and has spread to other anatomic sites. "In this study, we demonstrated that WDR62 is highly expressed in primary as well as metastatic prostate cancer and is associated with poor patient outcome." (PMID 34326322, 2021). "This is supported by our clinical data demonstrating WDR62 levels are not correlated with AR levels in metastatic prostate cancer." (PMID 34326322, 2021).
Premature ovarian insufficiency (2 papers, 2018 to 2021). Amenorrhea due to loss of ovarian function before the age of 40. "More importantly, two novel mutations of the WDR62 gene were detected in patients with premature ovarian insufficiency (POI), and these mutations played dominant-negative roles in regulating Stra8 expression." (PMID 30102701, 2018).
Seckel syndrome (2 papers, 2016 to 2021). A rare autosomal recessive inherited syndrome caused by mutations in the ATR gene, RBBP8 gene, CENPJ gene, CEP152 gene, CEP63 gene, NIN gene, DNA2 gene, or TRAIP gene. "Here, we have provided evidence that heterozygous missense variants of WDR62, CEP63 and RAD50 aggravate the phenotype of MCPH and a PCNT nonsense variant exacerbates the severity of Seckel syndrome features." (PMID 34068194, 2021). "Here, we propose that heterozygous variants of WDR62, CEP63, RAD50 and PCNT contribute to additional neurological and extra-neurological abnormalities in affected siblings of the families manifesting MCPH or Seckel syndrome." (PMID 34068194, 2021).
adenoma (1 paper, 2024). A neoplasm arising from the epithelium. "Noteworthy, the numbers of RNA interactors of some MP-RNAs (WDR62, TGFBR3, RN7SL5P, RMRP, MIR663AHG, AJ009632.2, CDKL1, OPRD1, PLOD1, AL117692.1, ATP13A2, EPB41) in cancer tissue were significantly increased compared with that in paracancer and adenoma." (PMID 38773399, 2024).
atrial septal defect (1 paper, 2015). Interauricular communication is a congenital malformation characterized by a communication between the atrial chambers of the heart. "Pure 17q25.3 submicroscopic copy number gains are also infrequent, and have been observed in association with distal arthrogryposis, craniofacial dysmorphism and atrial septal defect (ASD); intellectual disability; and with severe microcephaly with concurrent mutation in WDR62." (PMID 26070612, 2015).
autism (1 paper, 2023). Persistent deficits in social interaction and communication and interaction as well as a markedly restricted repertoire of activity and interest as well as repetitive patterns of behavior. "WDR62 is associated with intellectual disability and is listed as a high-risk gene for autism based on six support vector machine classifiers trained using different types of control gene lists." (PMID 36571716, 2023). "Intriguingly, the expression profile of 48 autism-associated DEGs in Wdr62+/− mice was partially reversed in Wdr62+/− mice brains with RA treatment." (PMID 36571716, 2023). "However, whether WDR62 deficiency impaired E/I balance and conditional deletion of WDR62 in the inhibitory circuit will contribute to autism-associated behavior still needs to be explored." (PMID 36571716, 2023). "Among the 569 downregulated genes in Wdr62+/− mouse cortex, 48 genes were associated with autism according to the SFARI (Simons Foundation Autism Research Initiative) autism database." (PMID 36571716, 2023). "Considering that the WDR62 mutations associated with autism are heterozygous, we examined ASD-related behaviors in heterozygous WDR62 mutant mice." (PMID 36571716, 2023). "Interestingly, we noted that a small population of heterozygous Wdr62-KO mice exhibited a higher frequency of repetitive circular locomotion, which indicated autism-like behavior." (PMID 36571716, 2023).
autoimmune disease (1 paper, 2025). A disorder resulting from loss of function or tissue destruction of an organ or multiple organs, arising from humoral or cellular immune responses of the individual to their own tissue constituents. "Genes such as DBH, WDR62, NRG1, and FER1L4, identified in hepatic and blood immune transcriptomes, were also implicated in a broad range of disorders, including major depressive disorder, autoimmune diseases, and cancer, which have been previously associated with hepatitis." (PMID 41347690, 2025).
cervical cancer (1 paper, 2021). A primary or metastatic malignant neoplasm involving the cervix. "Based on Kaplan‐Meier analysis, PCBP1-AS1 and four mRNAs (FAM222A, FHAD1, WDR62, and SBK1) were identified as potential prognostic factors for cervical cancer patients." (PMID 33833992, 2021).
chronic hepatitis (1 paper, 2025). An active inflammatory process affecting the liver for more than six months. "Genes like NRG1, OLFM1, and WDR62, associated with both tumor progression and neuropsychiatric symptoms such as fatigue and depression, highlight the neuroimmune signature as a potential marker of disease severity and a target to mitigate extrahepatic manifestations in chronic hepatitis." (PMID 41347690, 2025).
ciliopathy (1 paper, 2022). A genetic disorder of the cellular cilia or the cilia anchoring structures, the basal bodies, or of ciliary function. "Wdr62 has evidence of being a novel second order ciliopathy gene through its interaction with an intermediary protein CEP63." (PMID 36456625, 2022). "Eight of the 140 potential ciliopathy genes had predicted secondary interaction with gold standard cilia proteins, Aplnr, Casr, Gcgr, Grm6, Med1(or Mbd4), Mlh1, Rxfp2, and Wdr62.." (PMID 36456625, 2022). "Histological and morphological evidence of phenotypes found in ciliopathies in knockout mouse lines are presented as examples (genes Abi2, Wdr62, Ap4e1, Dync1li1, and Prkab1)." (PMID 36456625, 2022). "Wdr62 homozygous KO mice had ocular, renal, and reproductive organ abnormalities consistent with ciliopathy." (PMID 36456625, 2022). "Five of these genes predicted to have ciliary interaction (Abi2, Wdr62, Ap4e1, Dync1li1, and Prkab1) had abnormal morphological features detected by imaging that are consistent with the spectrum of phenotypes observed in ciliopathies." (PMID 36456625, 2022).
Coronary artery atherosclerosis (1 paper, 2025). "Coronary artery atherosclerosis (LAD-lesion area) was positively correlated with WDR62 and MARS1 transcript levels, and negatively correlated with FGGY, PAQR8, and RPS20 transcript levels (p < 0.05)." (PMID 40709334, 2025).
dwarfism (1 paper, 2023). "In addition, Wdr62-KO mice showed dwarfism and a significant reduction in body and brain weight at one-month-old." (PMID 36571716, 2023).
glioma (1 paper, 2021). A benign or malignant brain and spinal cord tumor that arises from glial cells (astrocytes, oligodendrocytes, ependymal cells). "Univariate analysis and multivariate analysis of the correlation of the expression of CDC20, UBE2C, WDR62, DTL, HOXB4 and TRIM38 with OS among glioma patients." (PMID 33914773, 2021). "Our results showed that 25 of the differentially expressed URGs were related to survival in glioma patients; six genes, CDC20, UBE3C, WDR62, DTL, HOXB4, and TRIM38, were statistically significant with an AUC value greater than 0.7." (PMID 33914773, 2021).
Hyperkeratosis (1 paper, 2016). Hyperkeratosis is a histopathological term defining a thickened stratum corneum and may be present in many different skin conditions, with many possible overlaps. "In conclusion, we report the first case of MCPH2 in a patient who presented with early onset acanthosis and hyperkeratosis, with two underlying novel mutations in the WDR62 gene." (PMID 27852057, 2016).
male infertility (1 paper, 2021). The inability of the male to effect fertilization of an ovum after a specified period of unprotected intercourse. "Round spermatids that inherited two centrioles continue to undergo spermiogenesis; however, WDR62 deficiency in elongated spermatids resulted in manchette removal defect, therefore causing oligoasthenoteratospermia and male infertility." (PMID 34059773, 2021).
MPPH syndrome (1 paper, 2025). "Since both WDR62 and Akt3 mutations impinge upon Aurora B, Aurora B dysfunction may be a key regulator of MPPH syndrome." (PMID 40048438, 2025).
Primary amenorrhea (1 paper, 2018). "We found two WDR62 heterozygous mutations by the screening of the whole exome sequencing in two patients with primary amenorrhea, and then we verified these mutations through Sanger sequencing." (PMID 30102701, 2018).
renal cell carcinoma (1 paper, 2022). "The research about the functional roles of NUMBL and WDR62 in renal cell carcinoma is seldom." (PMID 36159976, 2022).
Right ventricular hypertrophy (1 paper, 2022). In this case the right ventricle is more muscular than normal, causing a characteristic boot-shaped (coeur-en-sabot) appearance as seen on anterior- posterior chest x-rays. "Right ventricular hypertrophy could also be observed in some P1 Wdr62‐null mice." (PMID 35808830, 2022).